SENP6 (SUMO specific peptidase 6)
Description:
Protease that deconjugates SUMO1, SUMO2 and SUMO3 from targeted proteins. Processes preferentially poly-SUMO2 and poly-SUMO3 chains, but does not efficiently process SUMO1, SUMO2 and SUMO3 precursors. Deconjugates SUMO1 from RXRA, leading to transcriptional activation. Involved in chromosome alignment and spindle assembly, by regulating the kinetochore CENPH-CENPI-CENPK complex. Desumoylates PML and CENPI, protecting them from degradation by the ubiquitin ligase RNF4, which targets polysumoylated proteins for proteasomal degradation. Also desumoylates RPA1, thus preventing recruitment of RAD51 to the DNA damage foci to initiate DNA repair through homologous recombination.
Synonyms: KIAA0797; SSP1; SUSP1
Tractability: Small molecule: it belongs to a druggable protein family. PROTAC: UniProt records ubiquitination sites on it; ubiquitination databases record sites on it; a small molecule that binds it is known.
Target class: Protease; Enzyme; Cysteine protease CE clan; Cysteine protease C48 family; Cysteine protease
Gene: Protein-coding gene on chromosome 6 (75,601,509 to 75,718,281, forward strand). Ensembl gene ENSG00000112701.
Subcellular location: Nucleus
Subcellular location (Human Protein Atlas): Nucleoplasm; Cytosol
Gene Ontology:
Molecular function: protein binding; SUMO-specific endopeptidase activity; cysteine-type peptidase activity
Biological process: protein desumoylation; protein modification by small protein removal; regulation of kinetochore assembly; regulation of spindle assembly; protein sumoylation; proteolysis
Cellular component: nucleoplasm; cytoplasm; nucleus
Genetic constraint (gnomAD): Loss-of-function variants: 13 observed, 64.28 expected, observed/expected ratio (o/e) 0.2, 90% interval 0.13 to 0.32. The upper end of that interval is the gene's LOEUF score, 0.32, which puts it in group 1 of 6, group 1 being the genes least tolerant of losing a copy. Missense variants: 775 observed, 816.99 expected, observed/expected ratio (o/e) 0.95, 90% interval 0.89 to 1.01. Synonymous variants: 229 observed, 278.01 expected, observed/expected ratio (o/e) 0.82, 90% interval 0.74 to 0.92.
Homologues: Orthologues: chimpanzee SENP6 (99% identical), macaque SENP6 (97% identical), pig SENP6 (87% identical), rabbit SENP6 (85% identical), rat Senp6 (83% identical), guinea pig SENP6 (82% identical), mouse Senp6 (81% identical), dog SENP6 (54% identical), tropical clawed frog senp6 (52% identical), zebrafish senp6b (22% identical), zebrafish senp6a (21% identical), Drosophila melanogaster pira (16% identical), and 1 more. Paralogues in human: SENP7 (24% identical).
Diseases named in the same sentence as SENP6 in open-access papers:
SENP6 is named in the same sentence as 42 diseases in open-access papers, as found by Europe PMC text mining. Sharing a sentence is not in itself a finding about the gene and the disease. The quoted sentences say what the papers report.
lymphoma (5 papers, 2016 to 2025). A malignant (clonal) proliferation of B- lymphocytes or T- lymphocytes which involves the lymph nodes, bone marrow and/or extranodal sites. "Accordingly, SENP6 is critical for the genome integrity in murine as well as in human lymphomas, and deficiency of SENP6 leads to a significant increase of somatic DNA copy number variations." (PMID 35022408, 2022). "As expected, we detected insertions and deletions (InDels) with associated loss of SENP6 protein in Senp6-sgRNA lymphomas." (PMID 35022408, 2022). "Because several PARP inhibitors are approved for clinical use in other indications, PARPi could rapidly be investigated in clinical trials as a therapeutic option for patients with SENP6-deficient lymphoma." (PMID 35022408, 2022). "Notably, SENP6 is recurrently deleted in human lymphomas and SENP6 deficiency results in unrestricted SUMOylation." (PMID 35022408, 2022). "In line with the suggested function as a tumor suppressor, Senp6 mRNA expression was significantly lower in A/R/M lymphomas with transposon insertions in Senp6." (PMID 35022408, 2022). "SENP6 protein expression was substantially elevated in Eμ-myc lymphomas in comparison to normal B-cells." (PMID 35022408, 2022). "We also identified SENP6 deletions in a broad range of BCL sub-entities, including marginal zone (4.2%), mantle cell (7.7%), follicular (15.6%), and Burkitt lymphoma (6.5%), indicating a possible role of SENP6 or the SUMOylation pathway in other lymphomas." (PMID 35022408, 2022). "The high level of SUMOylated proteins in Eμ-myc lymphomas was further enhanced upon deletion of Senp6." (PMID 35022408, 2022). "To test if SENP6 is involved in the response to MYC-induced oncogenic stress, we analyzed SENP6 protein expression in murine MYC-driven lymphomas." (PMID 35022408, 2022). "Intriguingly, in comparison to control lymphomas, Senp6-sgRNA lymphomas showed a significantly larger genome fraction with SCNAs." (PMID 35022408, 2022). "In summary, this suggests that SENP6 serves as a gatekeeper of genome stability in both murine and human lymphomas." (PMID 35022408, 2022). "PARPi sensitivity of SENP6-deficient lymphoma cells was shown to be predominantly, but not completely RNF4-dependent, suggesting that RNF4-independent regulation of some DDR proteins by SENP6 is also important for maintaining genomic integrity." (PMID 37735495, 2023). "Syngeneic wild-type mice receiving Senp6 sgRNA FL-HSPC grafts were monitored for lymphoma onset." (PMID 35022408, 2022). "Given the abundant expression of Rnf4 in MYC-driven lymphomas, we hypothesized that co-depletion of RNF4 and SENP6 may impair PARPi sensitivity." (PMID 35022408, 2022). "Moreover, we also found SENP6 deletions with a frequency of 29% (14/48) in a second DLBCL dataset (TCGA DLBCL dataset), underscoring the relevance of the screening result for human lymphomas." (PMID 35022408, 2022).
hepatocellular carcinoma (4 papers, 2014 to 2025). A malignant tumor that arises from hepatocytes. "SENP6 was previously reported to induce radiosensitization of hepatocellular carcinoma cells by blocking radiation-induced NF-κB activation." (PMID 24926368, 2014). "For instance, promoter hypomethylation of SENP6 induces expression of SENP6 in hepatocellular carcinoma (HCC) tissues, and elevated SENP6 mRNA and protein levels are associated with promotion of HCC tumorigenesis." (PMID 34503213, 2021).
breast carcinoma (3 papers, 2016 to 2022). "Sentrin-specific protease 6 (SENP6) mRNA expression is lower in breast cancer tissue than in normal tissue." (PMID 35408841, 2022). "Unlike prostate cancer, enhanced sumoylation is favored with onset of breast cancer and correlated with the reduced SENP6 mRNA levels found in several breast cancer tissue arrays." (PMID 27178176, 2016).
Cerebral ischemia (3 papers, 2021 to 2025). Restriction of arterial blood supply to the brain associated with insufficient oxygenation to support the metabolic requirements of the tissue. "In summary, our findings identified a previously unrecognized molecular mechanism by which SENP6 participates in neuronal apoptotic death after cerebral ischemia." (PMID 34158860, 2021). "As expected, the results also showed that the colocalization of endogenous SENP6 with ANXA1 in the cortex region of mice was significantly increased after cerebral ischemia." (PMID 34158860, 2021). "We then conducted experiments to explore the effect of SENP6-mediated deSUMOylation of ANXA1 on neuronal damage after cerebral ischemia." (PMID 34158860, 2021). "Collectively, these results conclusively confirm that cerebral ischemia induces the expression of SENP6 at both the RNA and protein levels and deconjugates SUMO2/3 chains from the ANXA1 protein." (PMID 34158860, 2021). "Here, we showed that SENP6 functions as a specific isopeptidase of ANXA1 and that SENP6 could aggravate neuronal damage after cerebral ischemia." (PMID 34158860, 2021). "On the other hand, systemically administration with an inhibitor which could selectively downregulate SENP6 enzyme activity or block its interaction with ANXA1 may provide protective effects against cerebral ischemia-reperfusion injury." (PMID 34158860, 2021). "Given the critical role of SUMOylated ANXA1 in microglial polarization and the inflammatory response after cerebral ischemia, SENP6 may also play a role in these processes." (PMID 34158860, 2021). "Interestingly, cerebral ischemia enhanced SENP6 expression at both the RNA and protein levels in neurons and enhanced the binding of SENP6 with ANXA1 in vitro and ex vivo." (PMID 34158860, 2021). "The results of this study show that SENP6 inhibition may provide a novel and potential therapeutic strategy for treating cerebral ischemia." (PMID 34158860, 2021). "Importantly, inhibition of SENP6-mediated deSUMOylation of ANXA1 significantly improved neurological function after cerebral ischemia." (PMID 34158860, 2021). "SENP6 plays an important role in the regulation of genome stability, cell division, autoimmune responses, adult hematopoietic stem cell renewal and cellular senescence 56-61, but whether and how SENP6 plays a role in cerebral ischemia remains to be investigated." (PMID 34158860, 2021). "In addition, overexpression of WT SENP6, but not the SENP6 mutant, reduced the ANXA1 SUMOylation level, facilitated its nuclear and eventually led to neuronal apoptotic death after cerebral ischemia." (PMID 34158860, 2021).
ischemic stroke (3 papers, 2021 to 2025). A stroke disorder caused by obstruction of blood flow to the brain, due to thrombotic (local blood clot formation) or embolic (due to a blood clot or other material traveling from another site) event. "In the present study, we attempted to investigate whether SENP6 was crucial in oxidative stress after ischemic stroke and study its underlying mechanism." (PMID 39716997, 2025). "This study uncovers a previously unrecognized role for SENP6‐mediated deSUMOylation of Nrf2 in neuronal oxidative stress after ischemic stroke." (PMID 39716997, 2025). "Collectively, these results provide strong evidence that Nrf2 can be modified by SUMOylation and SENP6 effectively removes SUMO2/3 chains from Nrf2 following ischemic stroke." (PMID 39716997, 2025). "Collectively, these data suggest that SENP6 knockdown decreases oxidative stress injury and subsequently reduces neuronal damage after ischemic stroke." (PMID 39716997, 2025). "Collectively, these data revealed that SENP6 deSUMOylates Nrf2 at the C‐terminal residue K533 via a direct interaction after ischemic stroke." (PMID 39716997, 2025). "In a previous study, we identified that SENP6 aggravated neuronal apoptosis by de-SUMOylating ANXA1 after ischaemic stroke." (PMID 35869493, 2022). "This research systematically explored the function and potential mechanism of SENP6 in microglia-induced neuroinflammation after ischaemic stroke." (PMID 35869493, 2022). "Consistent with the in vitro data, qRT-PCR and immunoblots results also showed that the mRNA and protein level of SENP6 gradually increased after the onset of ischemic stroke." (PMID 34158860, 2021). "In light of this discovery, we further found that inhibition of SENP6, particularly in neurons, can alleviate neuronal apoptosis and protect against ischemic stroke." (PMID 34158860, 2021). "Furthermore, the in vivo evidence revealed that the disruption of the binding between SENP6 and Nrf2 using the Tat‐Nrf2 peptide leads to a significant decrease in brain injury and alleviated neurological outcomes in mice after ischemic stroke." (PMID 39716997, 2025). "We next study whether overexpression of Nrf2 could reversed SENP6‐iduced oxidative stress damage and neurotoxicity after ischemic stroke." (PMID 39716997, 2025). "Additionally, the upregulation of Nrf2 SUMOylation via SENP6 knockdown protected against oxidative stress‐trigged neuronal apoptosis after ischemic stroke." (PMID 39716997, 2025). "We first examined whether AAV-mediated knockdown of SENP6 altered the phenotype polarization of microglia in ischaemic stroke mice." (PMID 35869493, 2022). "Specific intervention of SENP6 activity in microglia could reduce neurological injury after cerebral ischaemia, suggesting that intervention with SENP6 may be a new and promising strategy for ischaemic stroke treatment." (PMID 35869493, 2022). "In addition, downregulation of SENP6 in microglia effectively reduced cocultured neuronal damage induced by ischaemic stroke." (PMID 35869493, 2022). "Additionally, our previous study found that SENP6 in neurons promoted neuronal apoptosis by mediating the de-SUMOylation of Annexin-A1 (ANXA1) after ischaemic stroke." (PMID 35869493, 2022). "Thus, overexpression of WT SENP6 can exacerbate neuronal damage in mice subjected to ischemic stroke injury." (PMID 34158860, 2021). "More importantly, SENP6 inhibition by overexpression of a SENP6 catalytic mutant in neurons resulted in significant improvement in neurological function in the mouse model of ischemic stroke." (PMID 34158860, 2021). "Additionally, blocking the interaction between SENP6 and Nrf2 with a cell membrane‐permeable peptide (Tat‐Nrf2) preserves the SUMOylation of Nrf2, effectively attenuates oxidative stress, and rescues neurological functions in mice subjected to ischemic stroke." (PMID 39716997, 2025).
ischemic stroke (continued). "Collectively, this study uncovers a previously unidentified mechanism whereby SUMOylation of Nrf2 regulates oxidative stress and strongly indicates that interventions targeting SENP6 or its interaction with Nrf2 may provide therapeutic benefits for ischemic stroke." (PMID 39716997, 2025). "Overall, this study clarified a previously undiscovered role of SENP6 and indicated that SENP6 inhibition promoting microglial polarization to an anti-inflammatory phenotype may be a new and promising therapeutic method for ischaemic stroke or other neuroinflammatory diseases and disorders." (PMID 35869493, 2022). "However, whether SENP6 influences microglial phagocytosis after ischaemic stroke remains unclear and needs to be further explored." (PMID 35869493, 2022). "We demonstrated a previously unidentified mechanism by which SENP6-mediated ANXA1 de-SUMOylation regulates microglial polarization and our results strongly indicated that in microglia, inhibition of SENP6 may be a crucial beneficial therapeutic strategy for ischaemic stroke." (PMID 35869493, 2022). "Notably, SENP6 binds to and mediates the deSUMOylation of Nrf2, which in turn inhibits antioxidant response by enhancing ubiquitination‐dependent degradation of Nrf2, thereby reducing its transcriptional activity, inducing oxidative stress and aggravating neuronal apoptosis after ischemic stroke." (PMID 39716997, 2025). "Whether SENP6-mediated ANXA1 deSUMOylation has a role in microglial polarization and the inflammatory response after ischemic stroke warrants future investigation." (PMID 34158860, 2021). "Additionally, upregulation of SENP6 reduced the Nrf2 SUMOylation level, inhibited Nrf2/ARE signaling pathway dependent antioxidant response and eventually leading to neuronal apoptosis after ischemic stroke." (PMID 39716997, 2025).
diffuse large B-cell lymphoma (2 papers, 2022 to 2024). "Genetic alterations or instability in SENP6 have been reported in lymphomagenesis and diffuse large B-cell lymphoma." (PMID 39251997, 2024).
acute lung injury (1 paper, 2026). A condition of lung damage that is characterized by bilateral pulmonary infiltrates (pulmonary edema) rich in neutrophils, and in the absence of clinical heart failure. "In vivo, SENP6-deficient mice exhibit markedly enhanced inflammatory responses in lipopolysaccharide (LPS)-induced endotoxic acute lung injury (ALI) and alum-induced peritonitis." (PMID 41531891, 2026).
Alzheimer disease (1 paper, 2025). A progressive, neurodegenerative disease characterized by loss of function and death of nerve cells in several areas of the brain leading to loss of cognitive function such as memory and language. "Additionally, it is observed that CCCP treatment resulted in a decrease of SENP6 within mitochondria fraction, accompanied by increased TOM40 SUMOylation in the brains of 3×Tg‐Alzheimer's disease (AD) mice or Aβ1‐42 peptide‐stimulated cells." (PMID 40729740, 2025).
B-cell lymphoma (1 paper, 2022). "Together, our results link SENP6 loss to defective genome maintenance and reveal the potential therapeutic application of PARP inhibitors in B-cell lymphoma." (PMID 35022408, 2022). "Using a genome-wide transposon mutagenesis screen in a MYC-driven B-cell lymphoma model, we here identify the SUMO isopeptidase (or deconjugase) SENP6 as a tumor suppressor that links unrestricted SUMOylation to tumor development and progression." (PMID 35022408, 2022).
Fanconi anemia (1 paper, 2018). Fanconi anemia (FA) is a hereditary DNA repair disorder characterized by progressive pancytopenia with bone marrow failure, variable congenital malformations and predisposition to develop hematological or solid tumors. "This is consistent with the reports that SENP6 interacts with and desumoylates the RPA70 and Fanconi Anemia ID complex and thus facilitates replication fork processing during DNA repair." (PMID 29321472, 2018).
leukemia (1 paper, 2017). A malignant (clonal) hematologic disorder, involving hematopoietic stem cells and characterized by the presence of primitive or atypical myeloid or lymphoid cells in the bone marrow and the blood. "Interestingly, RUNX2, MBNL1, JMJD1C, SENP6, MEF2C, and ZEB2 are also hypomethylated in MLL-FP samples compared to either normal cells or other leukemias (not shown)." (PMID 28076791, 2017).
osteoarthritis (1 paper, 2018). A noninflammatory degenerative joint disease occurring chiefly in older persons, characterized by degeneration of the articular cartilage, hypertrophy of bone at the margins and changes in the synovial membrane. "Whether and how SENP6 plays a role in joint aging and in the pathogenesis of osteoarthritis is worthy of further study." (PMID 29321472, 2018).
peritonitis (1 paper, 2026). Inflammation of the peritoneum (tissue that lines the abdominal wall and covers most of the organs in the abdomen). "SENP6 deficiency in vivo exacerbates LPS-induced endotoxic shock-associated lung injury and alum-induced peritonitis." (PMID 41531891, 2026). "focused on in vitro models, our study utilized in vivo models of ALI and peritonitis, offering a more complex, physiologically relevant context for observing SENP6’s role in NLRP3 regulation." (PMID 41531891, 2026). "We also assessed SENP6’s role in NLRP3-driven peritonitis via intraperitoneal alum injection." (PMID 41531891, 2026). "In vivo, SENP6 deficiency exacerbates NLRP3 activation and lung inflammation in lipopolysaccharide-induced endotoxic shock-associated lung injury, and enhances inflammatory responses in alum-induced peritonitis." (PMID 41531891, 2026). "(c) Phenotypically, SENP6 knockout significantly exacerbates LPS-induced ALI and alum-induced peritonitis." (PMID 41531891, 2026).
senile cataract (1 paper, 2020). A cataract with no obvious cause occurring in persons over 50 years old. "From these studies, we conclude that Ubc9, SENP6, and p32 Pax6 can be used as molecular markers for simple senile cataracts." (PMID 32827359, 2020).
Sepsis (1 paper, 2013). Sepsis is defined as life-threatening organ dysfunction caused by a dysregulated host response to infection. "Consistently, SENP6-knockdown mice were more susceptible to endotoxin-induced sepsis." (PMID 23825957, 2013).
trypanosomiasis (1 paper, 2024). Infection with protozoa of the genus trypanosoma. "Additionally, genes such as SENP6 and MYO6, associated with apoptosis and cellular transport, may contribute to the breed’s resilience against diseases like trypanosomiasis, common in their geographic area." (PMID 39119582, 2024).